FBXW7 (F-box and WD repeat domain containing 7)
Diseases named in the same sentence as FBXW7 in open-access papers (continued):
Sharing a sentence is not in itself a finding about the gene and the disease.
cancer (continued). "Previous studies have suggested that FBXW7 mutations strengthen the interaction among cancer-initiating cells via the NOTCH signalling pathway." (PMID 36936374, 2023). "Mutations of FBXW7 prevent the degradation and termination of pathways involving these proteins, leading to unabated cancer cell proliferation, and is the most commonly mutated protein in the SCF complex amongst human cancer cells." (PMID 37386001, 2023). "FBXW7 inactivation, resulting from mutations, deletions, or epigenetic modifications, is a major contributor to cancer progression and metastasis." (PMID 37408248, 2023). "FBXW7 plays a vital role in cellular division, and its downregulation is linked to cancer progression." (PMID 37752997, 2023). "Studies have shown that FBXW7-deficient leukemia-initiating cells (LICs) elevates the levels of c-Myc and are more sensitive to the anti-cancer drug imatinib." (PMID 38027013, 2023). "In human cells, FBXW7 has tumor suppressor functions and the gene is frequently mutated or silenced in cancers." (PMID 37681873, 2023). "The inactivation of genes involved in protein degradation such as tumor suppressor genes KEAP1 and FBXW7 has been previously implicated in sensitivity and resistance to cancer immunotherapy, respectively." (PMID 36669486, 2023). "FBXW7 inactivation in human cancers results from a somatic mutation or downregulation of its protein levels." (PMID 36934104, 2023). "In GC and other cancers, FBXW7 is frequently mutated and is associated with resistance to treatment and poor prognosis." (PMID 37408248, 2023). "FBXW7 is a tumor suppressor gene with mutations and deletions present across a wide range of cancers, most commonly in cervical, uterine, and colorectal tumors." (PMID 38032106, 2023). "The present study confirmed that loss of FBXW7 function effectively induced the proliferation and metastasis of cancer cells via MAP4-ERK-VEGFA." (PMID 36991467, 2023). "The FBXW7 gene is a tumor suppressor gene that undergoes mutation or deletion in a variety of human cancers, including colon, liver, lung, and ovarian cancer." (PMID 37176148, 2023). "According to our analyses from the COSMIC database data, the distribution of the most frequently found FBXW7 mutations in cancers is intriguingly different in different tissues." (PMID 35346215, 2022). "An increasing number of in vitro and in vivo studies has implicated that microRNAs can regulate cancer progression and therapeutic resistance by virtue of interacting with FBXW7, such as miR-223, miR-363, miR-27b-3p, and miR-92a-3p." (PMID 35515121, 2022). "In summary FBXW7 is implicated in essential pro-survival signaling pathways and exhibits an inextricable link to cancer progression." (PMID 35346215, 2022). "Although loss of FBXW7 is relevant to most human cancers, this section will focus on those most frequently associated cancers with FBXW7 mutations." (PMID 35346215, 2022). "Together, these experiments provide compelling evidence to support that FBXW7 deficiency leads to a profound MDR phenotype in human cancer cells." (PMID 35861150, 2022). "FBXW7 mutation has been discovered in plentiful human cancers including renal cell cancer, and it is one the 10 most frequently mutated genes in metastatic tissues of renal cancer." (PMID 35814468, 2022). "Here, we decipher the relationship between FBXW7 and the hallmarks of cancer and discuss the underlying mechanisms." (PMID 35515121, 2022). "According to the clinical information related to FBXW7 in the cBioportal database, of the TCGA Pan Cancer dataset, FBXW7 has mutations in a wide variety of cancers." (PMID 35346215, 2022).
cancer (continued). "Subsequently, inactivation of FBXW7 is a major cause of carcinogenesis and the development of human cancers." (PMID 35346215, 2022). "Intriguingly, the FBXW7 gene is often disrupted in different types of cancer or the WD40 domain is affected by missense point mutations." (PMID 35328741, 2022). "To test the impact of FBXW7 deficiency in the response to cancer therapies, we generated Fbxw7 wild‐type (WT) and knockout mES cell lines by CRISPR editing, which constitutively expressed the fluorescent proteins EGFP or RUBY3, respectively." (PMID 35861150, 2022). "In fact, FBXW7 is frequently inactivated or mutated in human cancers and inactivating mutations have been associated with resistance to therapies and poor prognosis for patients." (PMID 35346215, 2022). "Inactivation of FBXW7 by genetic mutation, genomic deletion, or promoter hypermethylation is a major cause of carcinogenesis and development of human cancers." (PMID 35346215, 2022). "This study reveals that while FBXW7 deficiency renders cells resistant to most chemotherapies, it also leads to mitochondrial stress and renders cancer cells vulnerable to drugs activating the integrated stress response (ISR)." (PMID 35861150, 2022). "Conversely, activation of the ISR has also been shown to stimulate mitochondrial translation, so that it is possible that the increased mitochondrial dependence of FBXW7‐deficient cancer cells is secondary to endogenous activation of the ISR in these cells." (PMID 35861150, 2022). "We found the association between NR1H3 expression and mutated FBXW7, which is one of the most frequently mutated genes in human cancers and its functional inactivation can lead to tumorigenesis." (PMID 36699456, 2022). "In fact, FBXW7 is one of the 10 most frequently mutated genes in human cancers, due to either inactivating mutations and/or allelic loss." (PMID 35861150, 2022). "Together, these experiments demonstrate that targeting mitochondrial function is particularly toxic for FBXW7‐deficient cancer cells." (PMID 35861150, 2022). "The human FBXW7 gene is localized at chromosome 4q32, a region deleted in 30% of cancers, and encodes three different isoforms (FBXW7α, β, and γ), derived from alternative splicing of the same transcript." (PMID 34760892, 2021). "Beside cancers, loss of FBXW7 also contributes to other mTOR-related diseases, such as metabolic disorders and aging, which warrants further studies." (PMID 33670113, 2021). "Diverse cancer‐associated mutations in FBXW7 and its substrates have been observed, and loss of FBXW7 function has been found to induce chromosomal instability during tumorigenesis." (PMID 33822486, 2021). "We revealed that FBXW7 mutations correlated with shorter DFS in the subgroup with advanced cancer stage." (PMID 33854094, 2021). "Some of these oncogenic substrates, such as c-MYC, NOTCH 1, MCL-1, Cyclin E, and c-JUN, likely play a driver role in FBXW7-associated cancers." (PMID 34760892, 2021). "FBXW7 mutations have been reported in several types of human cancers and found in 2.54% across all human tumors, according to COSMIC database meta-analyses." (PMID 33450701, 2021). "Accumulating studies have shown that FBXW7 dysregulation by point mutation, genomic deletion, or promoter hypermethylation leads to various cancers and that Fbxw7+/− mice are more prone to radiation-induced tumorigenesis." (PMID 33676554, 2021).
cancer (continued). "FBXW7 is a tumor suppressor extensively studied in different kinds of human cancers, that is deleted or mutated in various cancers." (PMID 35006464, 2021). "The question that we ask here is, can FBXW7 serve as a diagnostic marker in cancer, given its deregulated expression patterns in a range of tumors?" (PMID 33822486, 2021). "Collectively, these data reveal that SCF complex member genes are mutated in a diverse array of cancer types with FBXW7 being the most frequently mutated gene in many cases." (PMID 35008511, 2021). "F-box and WD repeat domain-containing 7 (FBW7), also known as FBXW7 or hCDC4, is encoded by the FBXW7 gene residing at chromosome 4q31 which is deleted in ~ 30% of human cancers." (PMID 33658012, 2021). "FBXW7 promotes mTOR ubiquitination/degradation in cancer cells and gliocytes, while FBXW7 deficiency increases the sensitivity of a variety of human tumors to rapamycin." (PMID 33291075, 2020). "Consistent with the notion that FBXW7 controls the degradation of many oncoproteins, loss of FBXW7 has been linked to increased drug resistance or sensitivity in cancer cells." (PMID 32907612, 2020). "Myc is a cancer-associated transcription factor that is targeted for proteasome-mediated degradation by the E3 ligase, Fbxw7." (PMID 32992762, 2020). "Although it is challenging to target specific FBXW7 mutants, the deregulation of distinct downstream targets as a result of FBXW7 mutations reveals unique cancer dependencies and provides opportunities for targeted personalized therapeutic intervention." (PMID 32907612, 2020). "A large amount of cancer-related mutations of FBXW7 have been verified in various cancers and loss of FBXW7 function leads to carcinogenesis." (PMID 32239181, 2020). "This E3 ligase requires three arginine residues (Arg465, Arg479, and Arg505) for substrate recognition and binding, with 29% of Fbxw7 cancer-associated mutations occurring at Arg465." (PMID 32992762, 2020). "FBXW7, the gene encoding FBW7, is frequently mutated in human cancers, which is unsurprising considering FBW7 regulates a variety of oncogenic substrates, including c-Myc, Notch, Cyclin E, and c-Jun." (PMID 31905981, 2019). "Mutation, deletion, and hypermethylation are the main causes for the inactivation of FBXW7 thereby resulting in cancer progression." (PMID 30791487, 2019). "FBXW7 is an established tumour suppressor gene and frequently mutated in many cancers, particularly endometrial and gastrointestinal cancers." (PMID 30885698, 2019). "Loss of FBXW7 greatly accelerates tumorigenesis, which results in a more cancer cell proliferative and less cell differentiation in CRC, hepatocellular carcinoma, gastric carcinoma, breast cancer, and so on." (PMID 31519156, 2019). "Although FBXW7 −/− mice are embryonic lethal, loss of FBXW7 inhibits cell division, stem cell differentiation, enhances chromosomal instability, and can cause cancer in hematopoietic cells." (PMID 30086763, 2018). "We hope that our data serves as a starting point to further examine cancer vulnerabilities, in particular in FBXW7‐, RB1‐, or NF2‐mutated tumors." (PMID 29689640, 2018). "Up to 6% of all human cancers bear mutations in FBXW7, and RB1 alterations occur in about 60–90% of sporadic small cell lung cancer cases, for instance." (PMID 29689640, 2018). "The catalytic activity of CDK2-CyclinE complexes is hyperactivated in several cancers by Cyclin E amplification, or a loss-of-function mutation of FBXW7, a ubiquitin ligase for Cyclin E degradation, although CDK2 mutations are rare in human cancers." (PMID 29540837, 2018). "The exploration of FBXW7 mutations in human primary cancer has revealed three mutation hotspots at conserved arginine residues (Arg465, Arg479, and Arg505) in the WD40 domain, which are critical for substrate recognition." (PMID 29386660, 2018).
cancer (continued). "Analyses of the Catalogue of Somatic Mutations in Cancer (COSMIC) database revealed that FBXW7 has the highest mutational frequency among all F-box and WD repeat domain containing family members and SCF ubiquitin ligase complexes." (PMID 30086763, 2018). "In the following sections, we will discuss the regulation of FBXW7, its role in oncogenesis, and the clinical implications and prognostic value of loss of function of FBXW7 in human cancers." (PMID 30086763, 2018). "Genetic profiles of human cancers based on high-throughput sequencing have revealed that FBXW7 is frequently mutated in human cancers." (PMID 30086763, 2018). "It is noteworthy that the FBXW7 gene is a well-known gene frequently mutated in various histological types of cancer." (PMID 29416628, 2018). "FBXW7 is a haplo-insufficient tumor suppressor, and is somatically mutated and/or deleted across a wide range of human cancers, with EC and T cell acute lymphocytic leukemias most frequently mutated." (PMID 29137450, 2017). "Comprehensive sequencing studies in EC have shown that FBXW7 mutations are more abundant in serous (15%-29%) and serous-like (21%) cancers, than in either clear cell (7%-13%) or endometrioid (10%-27%) ECs." (PMID 29137450, 2017). "FBXW7 mutations and deletions can cause chromosome instability and accelerate the accumulation of cancer cell proliferation associated genes such as Myc, CyclinE and Aurora-A." (PMID 28149200, 2017). "Deletion and/or mutations of FBXW7 have been found in cancers from a wide spectrum of human tissues." (PMID 27376155, 2016). "We conclude that Fbxw7-mutated cancer cells are highly proliferative and resistant to the terminal differentiation and subsequent cell death that is normally triggered by chemotherapeutic DNA damage." (PMID 27110583, 2016). "Rapidly accumulating data indicate that F-box/WD repeat-containing protein 7 (Fbxw7) is one of the most frequently mutated genes in human cancers and regulates a network of crucial oncoproteins." (PMID 26886596, 2016). "Loss of FBXW7 sensitizes cancer cells to certain drugs, while making them more resistant to other types of chemotherapies." (PMID 27110583, 2016). "Loss of FBXW7 function is likely to result in failed regulation of its downstream targets and cellular acquisition of the hallmarks of cancer." (PMID 25860929, 2015). "Our observations sustain the role of FBXW7 as cancer predisposition gene and expand the spectrum of its possible associated diseases." (PMID 26482194, 2015). "Their data showed that gene mutation leads to Fbxw7 inactivation in various types of human cancers, and overall mutation frequency was approximately 6%." (PMID 24884509, 2014). "In patients with advanced cancers, somatic mutations in FBXW7 usually occur with other simultaneous molecular aberrations, which can contribute to limited therapeutic efficacy of mTOR inhibitors." (PMID 24586741, 2014). "As the Fbxw7 null mutant mice do not faithfully recapitulate the mutations most commonly present in human cancers, we have generated a conditional Fbxw7 mutant mouse which carries one of the most commonly occurring propellor tip missense mutations." (PMID 23676439, 2014). "Several mechanisms have been reported for inactivation of FBXW7 in human cancer including mutation, deletion and hypermethylation." (PMID 23166673, 2012). "The majority of human FBXW7 alleles implicated in cancer are missense mutations and a missense mutation created in mouse Fbxw7 was functionally distinct from a null allele." (PMID 22554084, 2012).
cancer (continued). "FBXW7 gene mutations have been found in cancers from a wide spectrum of human tissues, such as bile duct, the haematopoietic system, bone, brain, breast, colon, endometrium, stomach, lung, ovary, pancreas, prostate, and head and neck." (PMID 22348067, 2012). "In order to test the specific effects of the arginine propeller tip mutations found in human cancers, we generated a mouse carrying an Fbxw7 point mutation and compared our mice with existing null Fbxw7 models." (PMID 21503901, 2011). "The majority of the mutations identified in Fbxw7/hCdc4 in cancer specimens are missense mutations in the binding pocket of Fbxw7/hCdc4 that prevent its interaction with the phosphorylated CPD motif in the target proteins." (PMID 21122106, 2010). "FBXW7 is mutated in many cancer cell lines and human tumors such as endometrial, pancreatic and colorectal cancers." (PMID 17326833, 2007). "Loss of FBXW7 in other cancers (lung, colon, and hematopoietic) has been linked to resistance to chemotherapeutic agents and poorer disease outcomes, but its significance in PCAC remains unclear." (PMID 39949429, 2025). "Interestingly, mTOR inhibitors have been shown to suppress EMT and cancer stem cell traits induced by FBXW7 mutations." (PMID 39749199, 2024). "In addition, the Fbxw7-185aa protein encoded by circFBXW7 was found to decrease the proliferation and migratory capabilities of cancer cells by enhancing FBXW7 density and increasing c-Myc degradation." (PMID 39727990, 2024). "It is therefore interesting to hypothesize that FBXW7 mutations modulate the Notch pathway, although FBXW7 also targets other cancer-related proteins for degradation, including cyclin E and c-myc." (PMID 39613893, 2024). "Consistent with that, the FBXW7 gene appears mutated in a wide variety of cancers." (PMID 36477079, 2023). "Together, this evidence confirms our results and indicates that FBXW7 is certainly a tumor suppressor gene and that its mRNA levels could be proposed as diagnostic and prognostic markers in various cancer types, including and specially in GBMs." (PMID 37752997, 2023). "Only NFE2L2, CDKN2A, and FBXW7 were rarely mutated in normal samples than cancer samples." (PMID 36991467, 2023). "This may relate to the reduced latency of tumorigenesis in our model, or differing effects of Fbxw7 loss and heterozygous missense mutation, as has been demonstrated in other cancer types." (PMID 37589076, 2023). "We speculated that the tumorigenic effect of a cancer‐associated Fbxw7 missense mutation may be unmasked when combined with another driver." (PMID 37589076, 2023). "In human cancers, the FBXW7 gene is frequently silenced or mutated." (PMID 37681873, 2023). "It has been reported that Fbxw7 may be associated with organ fibrosis, cell cycle, differentiation, and apoptosis in lung fibrosis-associated cancer." (PMID 37744239, 2023). "While many have proven oncogenic function, it is currently unclear which drive tumorigenesis in the various cancer types in which FBXW7 is recurrently mutated, as these may vary by tissue." (PMID 37589076, 2023). "Given the previous literature linking FBXW7 mutations to resistance to various cancer therapies, we wondered to what extent these observations were reflecting a more general phenomenon and whether FBXW7 deficiency could lead to MDR." (PMID 35861150, 2022). "Hence, perturbation of FBXW7 expression is considered as one of the major causes of cancer development and progression." (PMID 35740538, 2022). "We here show that FBXW7 deficiency, one of the most frequent events in human cancer, increases the resistance to the vast majority of available anticancer therapies, likely contributing to the bad prognosis that is associated with FBXW7 mutations." (PMID 35861150, 2022). "Conversely, pathological up-regulation of MAPK pathways, which is a general hallmark in cancers, may contribute to the disease in its early stages before FBXW7 goes through some loss of function mutations." (PMID 35328741, 2022).